ATM (ATM serine/threonine kinase)
Diseases named in the same sentence as ATM in open-access papers (continued):
Sharing a sentence is not in itself a finding about the gene and the disease.
ataxia telangiectasia (continued). "The genetic disorder, ataxia‐telangiectasia (A‐T), is caused by loss of the homeostatic protein kinase, ATM, and combines genome instability, tissue degeneration, cancer predisposition, and premature aging." (PMID 37254625, 2023). "Ataxia telangiectasia (A-T) is an autosomal recessive IEI caused by biallelic mutation of ATM gene encoding for ATM protein that belongs to the family of phosphoinositide-3-kinase like kinase." (PMID 36756122, 2023). "Their parents, heterozygous carriers of pathogenic ATR variants, should also be monitored for cancer predisposition as it is done for heterozygous carriers of ATM pathogenic variant that cause ataxia-telangiectasia in a homozygous state." (PMID 36749285, 2023). "Biallelic ATM mutations underlie Ataxia Telangiectasia (AT) (MIM #08900), an autosomal recessive cancer prone disorder with neurological and immunological involvement." (PMID 37509701, 2023). "Patients with ataxia telangiectasia (A-T) caused by either ATM deficiency or mutation are prone to various cancers." (PMID 38012183, 2023). "Pathogenic loss-of-function (LOF) variants in the ATM gene are responsible for ataxia–telangiectasia, a rare autosomal recessive disorder characterized by neurodegeneration, increased sensitivity to radiation, immunodeficiency, and a predisposition to cancer." (PMID 38201513, 2023). "Biallelic germline variants in the ATM gene cause ataxia–telangiectasia, a disorder characterized by neuronal degeneration, immune deficiency, and increased cancer risk." (PMID 38201484, 2023). "For, example, patient number #16 had a positive ATM mutation classified as pathogenic and diagnosed with ataxia telangiectasia (A-T) at nine years old." (PMID 37878632, 2023). "Ataxia-telangiectasia (A-T) is an autosomal recessive genomic instability syndrome, resulting from a mutation of the Ataxia-Telangiectasia Mutated (ATM) gene encoding for the ATM kinase." (PMID 37667293, 2023). "The ataxia-telangiectasia mutated (ATM) protein kinase is, as the name implies, mutated in the human genetic disorder ataxia-telangiectasia (A-T)." (PMID 35453338, 2022). "Ataxia-telangiectasia (A-T) is an autosomal recessive, multi-system, progressive andlife-shortening disease due to mutations in the ataxia-telangiectasia mutated (ATM)gene on chromosome 11q.26." (PMID 35290391, 2022). "Senescence was recently investigated in ataxia-telangiectasia, an ataxia caused by a mutation to ataxia-telangiectasia mutated (ATM), a kinase known to be a master regulator of the double-strand DNA break repair process." (PMID 36251631, 2022). "Ataxia-Telangiectasia (A-T), a genome instability disorder caused by biallelic mutations in the ataxia-telangiectasia mutated (ATM) gene, is a premature aging syndrome that in many aspects recapitulates human brain aging." (PMID 35247254, 2022). "Ataxia–telangiectasia (A–T) is an autosomal recessive disease caused by loss-of-function mutations in the ATM gene (A–T mutated)." (PMID 35212385, 2022). "Ataxia-telangiectasia is an autosomal recessive disorder that usually manifests in childhood due to mutations in the Ataxia-Telangiectasia Mutated (ATM) gene." (PMID 36547201, 2022). "Ataxia telangiectasia (A-T) is a DNA damage response disorder caused by mutations in the Ataxia telangiectasia mutated (ATM) gene." (PMID 35935942, 2022). "Homozygous ATM mutations cause ataxia telangiectasia (AT), the human syndrome associated with the highest radiosensitivity." (PMID 36551628, 2022). "Most of the ATM mutations demonstrated here are nonsense mutations, as are seen in ataxia telangiectasia, that likely lead to a loss of function." (PMID 36514795, 2022). "Germline variants in ATM are responsible for the cancer predisposition syndrome Ataxia Telangiectasia." (PMID 35456440, 2022). "It has been demonstrated that many advanced aging disorders are linked to mutations in DDR proteins, e.g., a mutation occurs in ATM causing Ataxia-Telangiectasia (AT)." (PMID 35457203, 2022).
ataxia telangiectasia (continued). "Ataxia telangiectasia (AT), which is caused by biallelic mutations of the ATM gene, affects multiple systems and leads to cerebellar degeneration, telangiectasia, immunodeficiency, and susceptibility to cancer." (PMID 35665206, 2022). "Ataxia-telangiectasia (A-T) is a rare autosomal recessive disorder caused by mutations in the ataxia telangiectasia mutated (ATM) gene." (PMID 34628594, 2022). "ATM gene homozygous or compound heterozygous DNA variants are associated to the onset of an autosomal recessive disease, namely ataxia telangiectasia, featured by a progressive cerebellar degeneration and oculo-cutaneous telangiectasia." (PMID 36035419, 2022). "ATM is the gene implicated in the development of ataxia-telangiectasia, a disease clinically characterized by ataxia, immunosuppression, and predisposition to malignancies." (PMID 36514795, 2022). "For some diseases, cryptic splicing variants are in fact very common such as POLR3A variants for recessive spastic ataxia, ATM variants for Ataxia telangiectasia, ABCA4 for Stargardt diseases, and NF1 variants for neurofibromatosis." (PMID 34591693, 2022). "Pathogenic ATM variants act in a recessive manner to cause Ataxia telangiectasia (a neurodegenerative disease), whereas heterozygous carriers are at moderately increased risk for breast cancer." (PMID 35039564, 2022). "Ataxia telangiectasia (AT) is a rare neurodegenerative genetic disorder due to bi-allelic mutations in the Ataxia Telangiectasia Mutated (ATM) gene." (PMID 35257272, 2022). "Ataxia telangiectasia is an autosomal recessive genetic disease that is closely related to ATM mutations." (PMID 34926254, 2021). "Truncated mutations in the ATM gene inhibit its expression and cause Ataxia Telangiectasia; however, missense mutations change its function and are common in cancers." (PMID 34493284, 2021). "Loss of ATM function results in the autosomal recessive disorder ataxia-telangiectasia (A-T), which causes ataxia due to cerebellar neuron cell loss and telangiectasia." (PMID 34356379, 2021). "In humans, low expression or inactivation of ATM causes ataxia-telangiectasia (A-T), a neurodegenerative syndrome associated with growth retardation, cancer predisposition, immune response deficiency, and genomic instability." (PMID 34422791, 2021). "Mutations in the ATM, which encodes a serine/threonine kinase activated in response to DNA damage, cause ataxia telangiectasia (AT)." (PMID 33512317, 2021). "The first syndrome that provided a direct link between DNA damage and neurological abnormalities is ataxia telangiectasia (AT), an inherited syndrome caused by mutation to ATM." (PMID 34899270, 2021). "For example, there are patients with pathogenic ATM alleles, which are known to cause the congenital disease ataxia-telangiectasia (ATS), which also convey an increased risk of developing cancer." (PMID 33747920, 2021). "ATM deficiency is also linked to increased oxidative stress within the cerebellum, the brain region heavily affected in Ataxia Telangiectasia patients." (PMID 34210972, 2021). "Ataxia-telangiectasia (AT) is a primary immunodeficiency disease caused by mutations in AT mutated (ATM) gene encoding a serine/threonine protein kinase." (PMID 33733696, 2021). "Ataxia-telangiectasia is a rare autosomal recessive, neurodegenerative disorder caused by alterations in the ATM gene." (PMID 34404412, 2021). "In particular, ATM gene mutations are the most frequent cause of ataxia telangiectasia, an autosomal recessive disorder characterized by cerebellar degeneration." (PMID 34193871, 2021). "Ataxia-telangiectasia (A-T) is a progressive neurodegenerative disease caused by mutations in the ataxia telangiectasia mutated (ATM) gene." (PMID 34631213, 2021). "Most of the ATM variants associated with Ataxia Telangiectasia are still classified as variants with uncertain significance." (PMID 34759960, 2021).
ataxia telangiectasia (continued). "Of note, most of ataxia-telangiectasia patients carry hereditary heterozygote or homozygote ATM mutations from each parent." (PMID 34070860, 2021). "ATM (ataxia telangiectasia, mutated) is essential for DNA repair, and its defects lead to ataxia telangiectasia (AT) with multisystem syndrome, including combined immunodeficiencies." (PMID 34887872, 2021). "Biallelic ATM inactivation causes ataxia-telangiectasia while heterozygous variants moderately increase the risk of several tumors including breast or pancreatic cancers." (PMID 34503238, 2021). "Meanwhile, ataxia-telangiectasia (A-T) is caused by inactivating mutations in ATM, the gene that lies next to NPAT on chromosome 11, and is associated with metabolic dysfunction, leading to insulin resistance, diabetes and fatty liver." (PMID 34197485, 2021). "Germ-line mutations of the ataxia telangiectasia mutated (ATM) gene result in the well-characterized ataxia telangiectasia syndrome, which manifests with an increased cancer predisposition." (PMID 33909629, 2021). "The ATM protein kinase is best known for its role as a chief mobilizer of the cellular response to this DNA lesion, and biallelic pathogenic ATM variants cause Ataxia Telangiectasia." (PMID 34350294, 2021). "Ataxia Telangiectasia (AT) is a rare autosomal recessive disorder caused by biallelic mutations in the ATM gene." (PMID 34759960, 2021). "Ataxia telangiectasia (AT) is a primary immune deficiency caused by mutations in the ATM gene, involved in the repair of double-strand breaks." (PMID 34183044, 2021). "Mutations of the ATM gene leads to deficiencies in the DNA-damage response, which results in the development of ataxia telangiectasia, a rare hereditary autosomal recessive disorder with a 1 in 40,000 to 300,000 frequency in Caucasians." (PMID 34070860, 2021). "Mutations in ATM result in the genetic disorder ataxia-telangiectasia (AT), which is characterized by the high sensitivity of AT patients to IR and cancer predisposition." (PMID 33898418, 2021). "Ataxia telangiectasia (AT) is a rare PID caused by mutations in the Ataxia Telangiectasia Mutated (ATM) gene, involved in the DNA damage response (DDR)." (PMID 34183044, 2021). "Ataxia telangiectasia (AT) is a progressive neurodegenerative disease caused by ataxia telangiectasia mutated (ATM) gene mutation." (PMID 32850797, 2020). "Despite that the human autosomal recessive disease ataxia telangiectasia (A-T) is a rare pathology, interest in the function of ataxia-telangiectasia mutated protein (ATM) is extensive." (PMID 32858941, 2020). "Cells from patients with ataxia-telangiectasia (an ATM-deficiency disease) or Nijmegen breakage syndrome (an NBS1-deficiency disease) display abnormal intra-S-phase checkpoints and RDS." (PMID 32434870, 2020). "Mutations in ATM are found in ataxia-telangiectasia (A-T) patients and ATM is one of the most frequently mutated genes in many cancers." (PMID 31740029, 2020). "The genetic basis of the neurodegenerative disorder ataxia-telangiectasia (AT) is the loss of the AT mutated (ATM) gene, which is the master regulator of the DNA damage response." (PMID 32518230, 2020). "ATM is also the cause of ataxia-telangiectasia (AT), a rare autosomal recessive disorder characterized by neurodegeneration, radiation hypersensitivity, immunodeficiency, and cancer predisposition." (PMID 31963441, 2020). "The ATM serine/threonine kinase (ATM) gene is involved in the activation of the DNA damage checkpoint, and mutations in this gene are responsible for the autosomal recessive syndrome ataxia-telangiectasia." (PMID 33112566, 2020). "Ataxia-Telangiectasia (A-T), a pleiotropic chromosomal breakage syndrome, is caused by the loss of the kinase Ataxia-telangiectasia mutated (ATM)." (PMID 33338048, 2020).
ataxia telangiectasia (continued). "Individuals homozygous for ATM germline mutations can develop Ataxia Telangiectasia, which includes susceptibility to cancer within its disease spectrum, and mutations in ATM in a heterozygote state have been implicated in cancer susceptibility." (PMID 32393777, 2020). "We report novel ATM gene variants that have implications on the molecular diagnosis of ataxia telangiectasia." (PMID 33376610, 2020). "Ataxia-telangiectasia is an autosomal recessive primary immunodeficiency disease that is caused by mutations in ataxia-telangiectasia mutated (ATM) gene encoding a serine/threonine protein kinase." (PMID 33292572, 2020). "Ataxia Telangiectasia is a rare inherited disorder caused by mutations in the Ataxia Telangiectasia Mutated (ATM) gene, coding for the homonym protein involved in cell division and DNA repair." (PMID 32168822, 2020). "Critically, mutations in ATM are found in ataxia-telangiectasia (A-T), a rare disease primarily associated with immunodeficiency and progressive neurological decline." (PMID 31740029, 2020). "Ataxia telangiectasia (A-T) is a disorder caused by mutations in the ataxia telangiectasia mutated (ATM) gene which controls cell division and DNA repair." (PMID 32973968, 2020). "The ATM protein was known to cause devastating ataxia-telangiectasia syndrome which is characterized by progressive neurological disorder, impaired organ maturation and immunodeficiency." (PMID 32509463, 2020). "While biallelic mutations of ATM cause ataxia telangiectasia syndrome, monoallelic mutations predispose cancer." (PMID 32283892, 2020). "In this study, we describe 6 novel ATM gene variants in 4 patients with clinical features of ataxia telangiectasia using next generation sequencing." (PMID 33376610, 2020). "Molecular cloning and functional analysis of SATMF (suppressor of atm in fertility) will help to understand the underlying regulatory mechanism of ATM in plants, and shed light on developing new treatments for the disease Ataxia-telangiectasia." (PMID 33143308, 2020). "Mutations in ATM are known to cause Ataxia telangiectasia syndrome, a multisystem disorder characterized by progressive neurological impairment, immunodeficiency, hypersensitivity to X-rays, and predisposition to several cancers." (PMID 32605254, 2020). "In a more extreme case, mutations in the DSB repair gene ataxia telangiectasia mutated (ATM) in the neurodegenerative disease ataxia telangiectasia (AT) leads to hypersensitivity to IR." (PMID 32731592, 2020). "Genome-wide and molecular studies have shown that alterations in the DNA-damage response (DDR) from ATM (ataxia-telangiectasia mutation) mutations influence intraindividual variations to radiation toxicity." (PMID 33008348, 2020). "The increase in γ-H2AX phosphorylated at Ser139 by protein kinase ATM (mutated in ataxia-telangiectasia) leads to the recruitment of the mediator of DNA damage checkpoint protein 1 (MDC1) as a response to the formation of double strand breaks (DSB)." (PMID 32357578, 2020). "More importantly, development of pulmonary fibrosis has been observed among patients with Ataxia-Telangiectasia (mutation in the central DSB/R molecule ATM), and telomerase dysfunction has been causatively linked with familial idiopathic pulmonary fibrosis." (PMID 33123169, 2020). "Another example of the association of DDR with aging is ataxia–telangiectasia (AT), underlined by mutations in the ATM (ATM serine/threonine kinase, ataxia telangiectasia mutated) gene." (PMID 33266495, 2020). "Bi-allelic P/LP variants in the ATM gene cause Ataxia–Telangiectasia (AT), a neurodegenerative progressive disease complicated by immunodeficiency and cancer predisposition." (PMID 32957588, 2020). "It is well known that mutations of the ATM gene cause ataxia telangiectasia, manifested by genomic instability, disorders of cell proliferation, and increased sensitivity to DNA damage." (PMID 31597313, 2019).
ataxia telangiectasia (continued). "Neurodegeneration in ataxia telangiectasia (A-T) patients is caused by inheriting mutations in the ATM (A-T mutated) gene, which encodes for the ATM protein kinase." (PMID 31771614, 2019). "Mutations in the ATM gene are recognized to cause ataxia-telangiectasia, a complex genetic neurodegenerative disorder characterized by cerebellar degeneration, telangiectasia, immunodeficiency, cancer susceptibility and increased radiation sensitivity." (PMID 31756226, 2019). "The majority of cases of fatal post-radiotherapy events were encountered after whole-body irradiation of children with ataxia telangiectasia (AT) caused by homozygous ATM mutations during their anti-leukemia or lymphoma treatment." (PMID 31717816, 2019). "The rare autosomal recessive disorder ataxia telangiectasia (A-T), caused by biallelic mutations in the ataxia-telangiectasia mutated (ATM) gene, is characterised by an extreme radiosensitivity, cancer predisposition and neurodegeneration." (PMID 31847107, 2019). "For example, ataxia telangiectasia and the related disorder Seckel syndrome are caused by mutations in the ATM and ATR genes, respectively, which encode two related protein kinases." (PMID 31788001, 2019). "Studies have also indicated that ATM‐deficient cells derived from ataxia–telangiectasia patients are distinctly sensitive to radiation and defective in DSB repair." (PMID 31152681, 2019). "One of the best-known examples is the severe and early-onset autosomal-recessive disorder ataxia telangiectasia, which is caused by mutations in the gene encoding ATM serine/threonine kinase (ATM), which is important for the repair of DNA double-strand breaks." (PMID 31230722, 2019). "Ataxia Telangiectasia (AT) is a rare, incurable, neurodegenerative disease caused by biallelic mutations in the ATM gene, which code for ATM, a protein of the PI3K family." (PMID 31107893, 2019). "Human mutations in the ATM gene are linked to ataxia-telangiectasia (A-T), a rare progressive neurodegenerative, autosomal recessive disease causing severe disability." (PMID 30700723, 2019). "Ataxia telangiectasia (AT) is a genetic condition caused by mutations involving ATM (Ataxia Telangiectasia Mutated)." (PMID 31921190, 2019). "Inherited pathogenic ATM mutation is the cause of autosomal recessive disease ataxia-telangiectasia which predisposes the individuals for increased cancer risk." (PMID 29769598, 2018). "Ataxia-telangiectasia is an autosomal recessive disorder caused by changes in the Ataxia-telangiectasia mutated (ATM) gene, which encodes an enzyme that contributes to DNA mismatch repair." (PMID 30319630, 2018). "While the sporadic form of T-PLL had been associated with somatic ATM mutations, it can also arise in cancer-predisposed adolescents with ataxia telangiectasia (A-T) that carry germline ATM inactivations." (PMID 29449575, 2018). "Mutations in the ATM gene are associated with ataxia telangiectasia (A-T), a human syndrome characterized by neurodegeneration, sensitivity to IR, immunodeficiency, and predisposition to cancer." (PMID 30501098, 2018). "A few recurring mutations in the ATM gene have been detected in Polish ataxia-telangiectasia patients." (PMID 29678143, 2018). "Ataxia-telangiectasia (A-T) is a rare autosomal recessive disorder caused by biallelic inactivating variants in the ataxia-telangiectasia mutated (ATM) gene." (PMID 29665859, 2018). "Ataxia telangiectasia (A-T) is a primary immunodeficiency with mutations in the gene encoding the A-T mutated (ATM) protein that interacts with immune, hematopoietic, and endocrine targets resulting in broad multi-systemic clinical manifestations." (PMID 30420857, 2018). "Ataxia Telangiectasia (A-T) is a rare genetic syndrome caused by mutations in the ataxia telangiectasia mutated (ATM) gene." (PMID 29608596, 2018).